TFAP2B (transcription factor AP-2 beta)
Diseases named in the same sentence as TFAP2B in open-access papers (continued):
Sharing a sentence is not in itself a finding about the gene and the disease.
craniosynostosis (1 paper, 2022). Craniosynostosis is defined as the premature fusion of one or more cranial sutures leading to secondary distortion of skull shape resulting in skull deformities with a variable presentation. "Subsequent protein analysis showed absence of TFAP2B protein for the constructs containing the deletion identified in the PIPO patient, as well as the nonsense variant identified in craniosynostosis." (PMID 35874825, 2022).
Hypocalcemia (1 paper, 2017). An abnormally decreased calcium concentration in the blood. "In this context, the findings in homozygous knockout mice of Tfap2b on the congenic 129P2 genetic background also included symptoms of kidney dysfunction like defective tubular secretory function and ion homeostasis, hypocalcemia, phosphatemia, hyperuremia, and terminal renal failure." (PMID 28818080, 2017).
lobular carcinoma (1 paper, 2023). "Notably, the expression of transcription factor TFAP2B, a luminal mammary epithelial differentiation marker and a well-established marker for lobular carcinoma that controls tumor cell proliferation in this slow-growing BC subtype, was detected." (PMID 37444409, 2023).
mental disorder (1 paper, 2019). A disease that has its basis in the disruption of mental process. "For example, TFAP2B is a member of the AP-2 family of TFs and is associated with neurological pathways and various mental disorders." (PMID 30930929, 2019).
myopia (1 paper, 2023). "We examined the top 64 myopia-associated loci that were expressed in the retinal layers and associated with common refractive errors, SNPs representing TSPAN10, KCNJ5, TFAP2B, and FBN2 had |nSL|> 2, which were under strong selection." (PMID 37919796, 2023).
orofacial clefting (1 paper, 2022). "Furthermore, these results indicate that AP-2α has the most potent TF activity since mice lacking Tfap2b, but containing one functional copy of Tfap2a, can still undergo normal facial development, whereas the reverse results in orofacial clefting." (PMID 35333176, 2022).
ovarian carcinoma (1 paper, 2025). A malignant neoplasm originating from the surface ovarian epithelium. "Our regression analysis identified six genes significantly associated with ovarian cancer: PI3, TFAP2B, MUC7, PSMA2, PIK3C2G, and NME1." (PMID 41154754, 2025).
polycystic kidney disease (1 paper, 2021). A usually autosomal dominant and less frequently autosomal recessive genetic disorder characterized by the presence of numerous cysts in the kidneys leading to end-stage renal failure. "TFAP2B has been linked to polycystic kidney disease and controls apoptosis of collecting duct and distal tubular epithelial cells in the metanephric kidney." (PMID 33976190, 2021).
rectal cancer (1 paper, 2023). A primary or metastatic malignant neoplasm that affects the rectum. "Interestingly, this miRNA regulates unique genes from all three anatomical locations, including CHGB in the right colon, CACNA1B and GLRA3 in the left colon, and TFAP2B in rectal cancer." (PMID 37987361, 2023).
tumor (27 papers, 2009 to 2025). "In NSCLC, both TFAP2A and TFAP2B are implicated in promoting tumor-induced angiogenesis via platelet-derived growth factor receptor (PDGFR), vascular endothelial growth factor receptor (VEGFR) and TGF-β signaling pathways." (PMID 37291585, 2023). "Meanwhile, TFAP2B methylation level was negatively associated with the changes in tumor maximal diameter and volume growth rate." (PMID 36555747, 2022). "Expression of TFAP2B was positively associated with lymph nodes metastases (p=0.003), distant metastases (p=0.002), recurrence of the tumor (p=0.002), unfavourable disease-free survival rate (p=0.003)." (PMID 32856873, 2020). "As expected, TFAP2B was the top highly expressed gene associated with fusion-positive tumours and was chosen for further analysis." (PMID 31493794, 2019). "The AP-2B (TFAP2B) transcription factor is overexpressed in LUAD and drives tumor growth via ERK and VEGF/PEDF signaling, associating with poor prognosis and plausibly regulating target motifs consistent with AP-2 binding." (PMID 41228248, 2025). "On the other hand, through analysis in LUSC patients, the significant differences were observed in TFAP2B transcript level according to tumor stage and age of patients." (PMID 36831334, 2023). "In RB, the expression of lncRNA TP73-AS1 is upregulated, and the downregulated TP73-AS1/miR-874-3p/TFAP2B axis can inhibit the Wnt/β-catenin signaling pathway, thereby inhibiting tumor progression." (PMID 35465322, 2022). "In RB tissues and cells, the TP73-AS1/miR-874-3p/TFAP2B axis can activate the Wnt/β-catenin signaling pathway and enhance the expression of downstream tumor-related factors TCF4, BCL2, CCND1, and MYC." (PMID 35465322, 2022). "At least two of these genes have evidence for tumor suppressor activity including the transcription factor TFAP2B and the protein tyrosine phosphatase PTPRH." (PMID 35246212, 2022). "In this study, we verified that TFAP2B regulates tumor growth in a cancer xenograft mouse model in vivo." (PMID 31113934, 2019). "Quantitative polymerase chain reaction (qPCR) analysis revealed higher levels of SOX11, FHAD1, HORMAD1 and TFAP2B expression in DCIS‐SOX11 than in DCIS‐LacZ tumours." (PMID 28707729, 2017). "The three transcripts, CACNA2D3, CNTNAP2 and TFAP2B, showed a 4–5 times lower expression in unfavourable tumour types." (PMID 19686582, 2009). "Only the methylation changes in PCDH8 and TFAP2B were related to the amount of tumor mass or the dynamics of tumor growth, thus may potentially supplement imaging data on SRMs’ growth." (PMID 36555747, 2022). "Therefore, in RMS both TFAP2B and ALK are functionally linked to PAX3/7-FOXO1 fusion positive tumours." (PMID 31493794, 2019). "Also, TFAP2B was recently suggested to be one of the genes discriminating between stroma-rich and stroma-poor neuroblastic tumours, in an approach similar to this study." (PMID 19686582, 2009). "Other frequently correlated components included TFAP2B, TFAP2D, TFAP2E, TFAP2A-AS1, Meiothermus, and Corynebacterium, with the DLBC tumor cohort exhibiting the highest number of identified relationships." (PMID 41373739, 2025). "Violin plots demonstrated significantly elevated activities of IRF5, IRF8, KLF2, TFAP2B, and MAFK in Zbp1−/− tumor cells, while E2F4 and ETV4 were preferentially activated in WT tumors." (PMID 41430036, 2025). "Most of the genes were down-regulated in tumor tissues, for example, EDN3, KCNA1, TFAP2B, and ANK3 genes were significantly down-regulated in KICH, COAD, HNSC, KIRC, THCA, and KIRP." (PMID 41174507, 2025). "Univariable analysis showed that age, molecular subtype, tumor TNM staging, TFAP2A, TFAP2B, TFAP2C and TFAP2E were important factors affecting the survival of BLCA patients." (PMID 37859819, 2023). "A few tumor cells resided in a neural crest-like state, as identified by co-localized SOX11 and TFAP2B regulon activities, and exhibited a low level of melanocytic regulon activity compared to intermediate, except for SOX10." (PMID 35903095, 2022).
tumor (continued). "OLFM4, SPINK8, CRYAB, KCNMA1, TFAP2B, and TFF1 were significantly upregulated during tumor progression in P8‐2 CTCs." (PMID 33377642, 2020). "Two additional OLIG2 positive cases showed inconclusive FISH results, but were positive for TFAP2B and ALK, what suggests that these tumours expressed fusion positive signature." (PMID 31493794, 2019). "Both cases were also positive for TFAP2B and ALK, what suggests that these tumours expressed fusion positive signature." (PMID 31493794, 2019). "For example, transcripts for suppressors TFAP2B AP-2 α/β, HLF (↓7.951 fold) and EDN3 (↓5.932 fold) were decreased in tumor cells compared to basal cells." (PMID 22280838, 2012). "The TFAP2B gene expression was mostly found in normal adjacent tissues obtained from KICH, KIRC, and KIRP patients, whereas this gene was severely underexpressed in paired tumor samples." (PMID 36831334, 2023). "The analysis of the TFAP2B gene expression level showed the negative correlation with tumor purity in patients with LUAD (p = 0.0126) and conversely, the positive correlation in LUSC tissues (p= 0.0024)." (PMID 36831334, 2023). "In addition, we identify some genes that have recurrent ASE outside of common SCNA regions, including TFAP2B and PTPRH, both of which have low expression in stage 4 disease and evidence for tumor suppressor activity." (PMID 35246212, 2022). "The expression of TFAP2B and COX-2 in tumor tissues was analyzed by IHC staining." (PMID 31113934, 2019). "TFAP2B was positive (> 50% of tumour cells) in 11 cases, intermediate (10–50% of tumour cells) in 3 cases and negative (< 10% of tumour cells) in 31 cases." (PMID 31493794, 2019). "Knockdown of TFAP2B by shRNA significantly suppressed tumor growth and tumor weight compared to the nonspecific shRNA treatment." (PMID 24766673, 2014). "TFAP2B was highly expressed in NSCLC cell lines and tumor tissues." (PMID 24766673, 2014). "Two tumours with solitary intermediate (10–50%) reaction for TFAP2B were fusion gene-negative." (PMID 31493794, 2019). "This tumour was fusion negative, showing increased copy number (up to 10 per cell) for PAX3, PAX7 and FOXO1 and displaying TFAP2B positive reaction." (PMID 31493794, 2019). "Our results indicate that TFAP2B, ALK and a novel marker OLIG2 may serve as surrogate markers for PAX3/7-FOXO1 status what is especially beneficial in cases where poor quality tumour tissue is not suitable for reliable genetic analyses or shows inconclusive result." (PMID 31493794, 2019).
cancer (18 papers, 2012 to 2025). A tumor composed of atypical neoplastic, often pleomorphic cells that invade other tissues. "Because the oncogene TFAP2B has been studied for several years, it has been clarified that TFAP2B expression can be associated with cancer prognosis." (PMID 31113934, 2019). "The mutation rates of different MHGs varied widely across cancer tissues, with ANK3 having the highest mutation rate (47%), followed by KEL (18%), TRPM7 (16%), KCNA1 (13%), CNNM2 (9%), CNNM1 (9%), TFAP2B (9%), CNNM4 (9%), XK (7%), and EDN3 (5%)." (PMID 41174507, 2025). "Due to relatively few studies regarding the roles of TFAP2B in cancer progression, we assessed the expression of AP-1." (PMID 32856873, 2020). "We also performed an anchorage-independent colony formation assay to confirm the effects of TFAP2B on cancer cell growth." (PMID 24766673, 2014). "The TFAP2B gene codes for the transcription factor AP-2 beta, a sequence-specific DNA-binding protein that has been recognized as an oncogene that mediates cancer cell proliferation, apoptosis, invasion, and migration via the COX-2 signaling pathway in vitro and in vivo." (PMID 33113958, 2020). "Among the TFAP2 family members, TFAP2A, TFAP2B, and TFAP2E interact with β-catenin to inhibit or promote oncogenesis in different types of cancers." (PMID 40837414, 2025). "Interestingly, we found that AP-2, in particular TFAP2B, is also enriched compared with previous screens against developmental enhancers and cytokine gene promoters, suggesting that this TF family may be more actively involved in cancer regulation." (PMID 39013578, 2024). "Among the 135 samples, TFAP2B, ARHGEF4, and RAPGEFL1 had the highest values in 60, 37, and 38 samples, respectively, and the highest values were defined as the fractions of cancer cells in the samples." (PMID 24312652, 2013). "This indicates that cancer microenvironment cells are characterized by a slightly higher expression of the TFAP2B gene in relation to LUAD cells and the situation is reversed in LUSC, in which higher expression of the TFAP2B gene is typical for cancer cells." (PMID 36831334, 2023). "Additionally, overexpression of TFAP2B stimulated VEGF/PEDF signaling pathway, which has a role in cancer progression." (PMID 32856873, 2020). "The DSV (g.4260 T > C) may create a binding site for zinc finger transcriptional repressor hypermethylated in cancer 2 (HIC2) and modify binding sites for TFAP2B and TFAP2C." (PMID 31775637, 2019). "Bioinformatics suggest that TFAP2B may specifically bind to the COX-2 promoter, modulating the tumorigenesis and development of cancer." (PMID 31113934, 2019). "However, TFAP2B in sample Et5T, ARHGEF4 in Et1T, Et2T, Et4T, and Et5T, and RAPGEFL1 in Et2T were not completely methylated, possibly due to heterogeneity among cancer cells." (PMID 24312652, 2013). "Therefore, the effect of the copy number alterations of TFAP2B, and RAPGEFL1 was considered to be minimal in the estimation of a fraction of cancer cells." (PMID 24312652, 2013). "Next, to test the phenotypic response to altering ALDH1A3 and TFAP2B, we found that ALDH1A3 KO led to decreased colony formation while ALDH1A3 OE increased colony formation in both A375 and C089, consistent with the pan-cancer effect of ALDH activity in cancer stem-like states." (PMID 38963759, 2024). "Although the role of TFAP2B in MCC has not been described, the TFAP2 family is known to play multiple roles in cancer development." (PMID 38398178, 2024).
head and neck tumors (1 paper, 2019). "Among the most impressive differences in TF activity, head and neck tumors display lower activities of FEV, TFAP2B and GATA2 and higher activities of TFEC, LEF1, and MAFB compared to SDHD-null tumors of other anatomical locations." (PMID 31234811, 2019).
TFAP2B also shares sentences with these, for which no sentence is quoted: Branchio-oculo-facial syndrome (2 papers); frontonasal dysplasia (2); Holt-Oram syndrome (2); -hand” (1); acute myeloid leukemia (1); adenocarcinoma (1); ADULT syndrome (1); Alzheimer disease (1); Anorexia (1); Anxiety (1); atherosclerosis (1); bulimia nervosa (1); Cantu syndrome (1); colorectal cancer (1); coronary artery disease (1); COVID-19 (1); cystic kidney (1); diffuse large B-cell lymphoma (1); DiGeorge syndrome (1); genetic disorder (1); glioma (1); Hashimoto thyroiditis (1); heart-hand syndrome (1); hyaline fibromatosis syndrome (1); hyperuricemia (1); Intellectual disability (1); kidney (1); limb-mammary syndrome (1); lymph node metastasis (1); malignant glioma (1).
A further 16 diseases each share a sentence with TFAP2B in 1 paper.